C1QTNF2 (C1q and TNF related 2)
Description:
Involved in the regulation of lipid metabolism in adipose tissue and liver.
Synonyms: CTRP2; zacrp2
Tractability: Antibody: UniProt places it where antibodies can reach, with high confidence; UniProt predicts a signal peptide or a membrane-spanning region; its Gene Ontology location is reachable by antibodies, with medium confidence.
Gene: Protein-coding gene on chromosome 5 (160,347,754 to 160,370,645, reverse strand). Ensembl gene ENSG00000145861.
Subcellular location: Secreted
Subcellular location (Human Protein Atlas): Centrosome; Golgi apparatus; Predicted to be secreted
Gene Ontology:
Molecular function: protein binding; identical protein binding; signaling receptor binding
Biological process: regulation of lipid metabolic process
Cellular component: extracellular region; protein-containing complex
Genetic constraint (gnomAD): Loss-of-function variants: 16 observed, 17.56 expected, observed/expected ratio (o/e) 0.91, 90% interval 0.62 to 1.38. The upper end of that interval is the gene's LOEUF score, 1.38, which puts it in group 5 of 6, group 1 being the genes least tolerant of losing a copy. Missense variants: 381 observed, 385 expected, observed/expected ratio (o/e) 0.99, 90% interval 0.91 to 1.08. Synonymous variants: 154 observed, 161.66 expected, observed/expected ratio (o/e) 0.95, 90% interval 0.83 to 1.09.
Homologues: Orthologues: chimpanzee C1QTNF2 (99% identical), macaque C1QTNF2 (99% identical), dog C1QTNF2 (97% identical), rabbit C1QTNF2 (96% identical), pig C1QTNF2 (96% identical), guinea pig C1QTNF2 (94% identical), mouse C1qtnf2 (94% identical), rat C1qtnf2 (94% identical), tropical clawed frog c1qtnf2 (73% identical), zebrafish c1qtnf2 (65% identical). Paralogues in human: C1QTNF7 (57% identical), C1QTNF9 (40% identical), C1QTNF9B (40% identical), COL10A1 (38% identical), COL8A1 (35% identical), OTOL1 (35% identical), COL8A2 (34% identical), ADIPOQ (34% identical), C1QB (31% identical), C1QTNF5 (31% identical), C1QC (30% identical), C1QL2 (29% identical), and 11 more.
Diseases named in the same sentence as C1QTNF2 in open-access papers:
C1QTNF2 is named in the same sentence as 19 diseases in open-access papers, as found by Europe PMC text mining. Sharing a sentence is not in itself a finding about the gene and the disease. The quoted sentences say what the papers report.
Obesity (5 papers, 2014 to 2024). Accumulation of substantial excess body fat. "Of particular interest, some of these upstream regulators have been associated with cardiometabolic traits (though not TG), such as hypercholesterolemia, T2D, heart failure, and hyperglycemia (SIRT6); obesity (C1QTNF2); and weight gain, cardiomyopathy, liver cirrhosis, and insulin resistance (MGLL)." (PMID 39251667, 2024).
Cirrhosis (1 paper, 2017). A chronic disorder of the liver in which liver tissue becomes scarred and is partially replaced by regenerative nodules and fibrotic tissue resulting in loss of liver function. "These animal model- and clinical cohort-based findings suggest that C1QTNF2 plays a protective role in cirrhosis progression." (PMID 28256512, 2017).
Hepatic fibrosis (1 paper, 2017). The presence of excessive fibrous connective tissue in the liver. "C1QTNF2, which we have associated with liver disease severity and prognosis, may be a factor that potentially influences the outcome of apigenin-based therapy in particular, and the biology of hepatic fibrosis in general." (PMID 28256512, 2017).
lung carcinoma (1 paper, 2022). "Medium staining detection of CDC42BPA and IRAK2 were found in both normal and cancer lung tissue in addition to SREK1 and C1QTNF2 which was observed in medium in normal tissue but higher in lung cancer tissue." (PMID 36194576, 2022). "Out of 12 hub genes, only 4 (IRAK2, SREK1, C1QTNF2 and DDX3Y) have shown significant gene expression in lung cancer compared to the normal tissues." (PMID 36194576, 2022).
retinal degeneration (1 paper, 2021). Degeneration of the retina. "C1qtnf2 is a member of the C1q and tumor necrosis factor related-protein (CTRP) superfamily reported to be involved in retinal inflammation and associated with late-onset retinal degeneration." (PMID 34440888, 2021).
C1QTNF2 also shares sentences with these, for which no sentence is quoted: cancer (2 papers); Coronary Artery Disease (2); dyslipidemia (2); Insulin resistance (2); asthma (1); cardiomyopathy (1); coronary artery stenosis (1); heart failure (1); Hypercholesterolemia (1); Hyperglycemia (1); liver cirrhosis (1); liver disease (1); lung disease (1); trauma (1).